FTO (FTO alpha-ketoglutarate dependent dioxygenase)
Diseases named in the same sentence as FTO in open-access papers (continued):
Sharing a sentence is not in itself a finding about the gene and the disease.
tumor (continued). "FTO enhances tumor progression by demethylating m6A on proliferation-related transcripts." (PMID 40977743, 2025). "From a disease perspective, altered m6Am levels have been observed in cancer, where FTO overexpression may drive oncogenic gene expression by removing m6Am and destabilizing tumor suppressor mRNAs." (PMID 40870000, 2025). "The tumor-suppressive function of FTO was mechanistically dissected in our study." (PMID 40970086, 2025). "Notably, FTO has been reported to play dual roles in cancer, acting as either an oncogene or tumor suppressor depending on the tumor type and cellular context." (PMID 41141648, 2025). "Moreover, consistent with the in vitro results, APOE knockdown obviously weakened the tumor growth promoted by FTO overexpression, as reflected by tumor weight and tumor volume." (PMID 39990672, 2025). "FTO inhibitors have shown significant efficacy in inhibiting tumor growth." (PMID 41446042, 2025). "Subsequently, we investigated whether TRIM17 influences tumor progression by modulating FTO protein expression and regulating the AKT/mTOR signaling pathway." (PMID 41145484, 2025). "Notably, FTO exhibits carcinogenic effects by enhancing tumor proliferation, migration, and invasion during pNENs development." (PMID 39990672, 2025). "utilized the fat‐mass and obesity‐associated protein (FTO) to epigenetically inhibit APOE expression in PTC, leading to the inhibition of glycolytic metabolism via the IL‐T/JAK/STAT3 signalling pathway and subsequent suppression of tumour growth." (PMID 39810624, 2025). "Given the oncogenic role of FTO in cancers, these agents may also exert anti-tumor efficacy, though further experiments are required." (PMID 40830264, 2025). "The previous studies suggest that FTO might contribute to tumor growth; hence, we performed gene and protein expression analysis on NSCLC cell lines to examine whether FTO is upregulated in EGFR-TKI-resistant cell lines." (PMID 40722726, 2025). "FTO knockdown inhibited GC cell growth in vitro and suppressed tumor growth in vivo." (PMID 39773744, 2025). "Studies have found that Von Hippel–Lindau-deficient cells expressing FTO reduced the m6A level of PGC-1α mRNA, stabilizing PGC-1α mRNA, restoring mitochondrial activity, promoting oxidative stress and ROS production, and thus inhibiting tumor growth." (PMID 40332101, 2025). "However, in ovarian cancer, FTO acts as a tumor suppressor by regulating cyclic AMP signaling, which is involved in stemness and tumor initiation." (PMID 40819127, 2025). "Although FTO has been identified as being highly expressed in various tumors and closely related to tumor progression, the molecular mechanism accounting for the upregulation of FTO in tumor tissues remains largely unknown." (PMID 40712780, 2025). "Results showed decreased tumor weight following FTO depletion." (PMID 39773744, 2025). "Furthermore, the depletion or inhibition of FTO exacerbates dermal fibroblasts senescence and accelerates skin aging." (PMID 40636284, 2025). "Highly expressed FTO in human BC tissues significantly facilitates tumor progression." (PMID 40823087, 2025). "Corresponding with SRSF6, FTO was also found to be overexpressed in tumor tissues in HNSC." (PMID 40712780, 2025). "To delve deeper into the impact of FTO on tumor proliferation, invasion, and metastasis, we proceeded to elevate endogenous FTO levels in MHCC97H and MHCCLM3 cells by employing FTO lentiviral vectors, thereby establishing HCC cell lines with stably overexpressed FTO." (PMID 40316995, 2025). "While the direct regulatory roles of FTO in T cells remain unclear, indirect effects have been reported in the context of tumors, where FTO influences T cell function by modulating tumor cells." (PMID 40234389, 2025). "FTO and ALKBH5 demethylation may affect the expression of genes associated with autophagy in OC and contribute to tumor proliferation and invasion." (PMID 39904996, 2025).
tumor (continued). "Similarly, the 18097 molecule specifically binds to the active site of FTO, elevates m6A levels, and suppresses tumor growth in vivo in a xenograft model of lung cancer." (PMID 40002173, 2025). "FTO inhibitors may also alter tumor cell invasiveness by affecting cell proliferation and survival, influencing their metastatic capacity." (PMID 39802639, 2025). "In vivo, FTO overexpression decreased tumor growth and metastasis." (PMID 40316995, 2025). "Additionally, immune cell-related gene expression models now provide deeper insights into tumor immune dynamics, while the role of FTO in promoting tumor neovascularization via m6A modification removal has been highlighted." (PMID 39861138, 2025). "Moreover, the small molecule inhibitor FB23-2, which targets FTO, suppressed tumor growth in a ccRCC mouse model, indicating that FTO is a potential druggable target and that FTO inhibitors hold therapeutic potential for tumor treatment." (PMID 38576024, 2024). "Furthermore, significant downregulation of the m6A eraser, FTO, was observed in mCRPC compared to both the localized tumor tissues and normal tissues." (PMID 38610981, 2024). "Inhibition of MIF expression then reduces the level of FTO to exert a tumor suppressor effect." (PMID 39033180, 2024). "Furthermore, overexpression of FTO attenuated the inhibitory effect of GAS5 on tumor growth in vivo." (PMID 38782769, 2024). "RNA methylation could regulate the innate immunity of the body, and targeting these methylation regulatory molecules (such as METTL3, METTL4, and FTO) can directly enhance tumor immunotherapy." (PMID 38442004, 2024). "Moreover, FTO in tumor cells can suppress the activity of CD8+ T cells, enabling tumor cells to evade immune surveillance." (PMID 39072324, 2024). "On the other hand, FTO exhibits tumor-suppressive functions in various cancer contexts." (PMID 39192357, 2024). "However, this triggers an overall rise in m6A levels in infected tumor cells via the IGF2BP3/MIB1/FTO feedback loop, ultimately leading to CSF3-mediated NETosis." (PMID 38167409, 2024). "Likewise, a range of FTO inhibitors have been found to exert significant anti-tumor effects in AML, primarily by suppressing cell proliferation and enhancing apoptosis." (PMID 39459530, 2024). "Moreover, PCa patients with low FTO expression often experience advanced disease and poor survival, suggesting that it acts as a tumor suppressor during PCa development." (PMID 39268470, 2024). "In 2017, FTO's role in tumor progression was first reported." (PMID 39445003, 2024). "FTO downregulation promoted tumor cell glycolysis, growth, metastasis, and tumorigenesis in mice." (PMID 38721006, 2024). "Moreover, ccRCC cell lines that were treated with miR-155 exhibited an inhibition of FTO, resulting in increased tumor cell proliferation." (PMID 38503745, 2024). "In addition, it has been found in breast cancer that FTO can inhibit the expression of β-catenin, which leads to tumor chemoradiation resistance." (PMID 39033180, 2024). "Therefore, they developed a small-molecule compound, called Dac51, which further disrupts glycolysis in tumor cells by inhibiting FTO activity." (PMID 39759516, 2024). "Due to its combined fluorescence labeling functionality and FTO inhibitory activity, compound 27 may serve as a potential tool molecule, facilitating research on the role of FTO in tumor-related signaling pathways." (PMID 38711100, 2024). "However, there are several inconsistencies regarding the functions of the FTO in tumor development and prognosis." (PMID 39136000, 2024). "FTO also plays a role in regulating tumor cell metabolism, immune evasion, and metastasis." (PMID 39192357, 2024). "FTO regulates BNIP3 to influence tumor growth and metastasis in breast cancer." (PMID 39363112, 2024). "Interestingly, circGPR137B which has tumor suppressor function in HCC produces a positive feedback loop with FTO to suppress tumor cells proliferation, invasion, metastasis, and colony formation." (PMID 38075202, 2024).
tumor (continued). "Additionally, FTO promotes tumor progression in liver, lung, breast, cervical, and colorectal cancers (CRCs) while acting as a tumor suppressor in renal, pancreatic, thyroid, and cholangiocarcinomas." (PMID 39445003, 2024). "It was also found by sequencing that SLC1A5, a glutamine transporter target of FTO, could selectively affect the survival and proliferation of tumor cells by stimulating metabolic reprogramming of VHL-deficient ccRCC cells." (PMID 39033180, 2024). "FTO expression was higher in Primary tumor group than Normal group." (PMID 38200441, 2024). "Patients with low FTO expression are more likely to be CD34 positive (indicating microvessel density), suggesting that the expression of FTO may regulate tumor angiogenesis." (PMID 39295872, 2024). "Conversely, FTO serves as a tumor suppressor in ovarian cancer." (PMID 39449798, 2024). "Targeting FTO activity or expression could suppress tumor growth and metastasis by disrupting the oncogenic signaling axis." (PMID 38956367, 2024). "In conclusion, the role of FTO in cancer is multifaceted, influencing not only tumor growth and progression through metabolic reprogramming and m6A RNA modification but also impacting treatment outcomes by contributing to resistance mechanisms such as chemo-radiotherapy." (PMID 39744011, 2024). "The escalation in neoplastic cell apoptosis, facilitated by the suppression of FTO via pharmacological intervention, could potentially unveil tumor neoantigens." (PMID 39449798, 2024). "Changes or dysfunction in FTO expression may contribute to the occurrence and development of various tumors, where it can act as either a tumour suppressor gene or oncogene." (PMID 38094306, 2023). "High levels of FTO were also found in the tumour tissues and databases of RCC patients." (PMID 37284313, 2023). "m6A demethylases fat mass and obesity-associated protein (FTO) and alkB homolog 5 (ALKBH5) were shown to play oncogenic roles in various cancers, and in vitro studies confirmed that FTO-specific inhibitors exhibited anti-tumour effects." (PMID 37958565, 2023). "In addition, in breast cancer tissues, FTO overexpression was significantly correlated with tumor size, peritumor lymphovascular infiltration, and lymph node metastasis." (PMID 38053093, 2023). "Moreover, FTO was supposed to mediated immune evasion via rewiring tumor glycolytic metabolism to restrict effector T cells functions." (PMID 36810281, 2023). "In addition, OSCC patients with high FTO expression had larger tumor volume, higher tumor node metastasis (TNM) stage, worse differentiation, and shorter survival time." (PMID 36793593, 2023). "FTO exerted a tumor suppressive role by inhibiting MTA1 expression in an m6A-dependent manner." (PMID 37391814, 2023). "Clinical data analysis exhibited a relationship between FTO and tumor stage in BC patients." (PMID 37861518, 2023). "Interestingly, inhibition of FTO significantly delays tumor progression and extends the life span of GSC-transplanted mice." (PMID 37007137, 2023). "Because we surprisingly found that both “writers” (METTL3, METTL14 and WTAP) and “erasers” (ALKBH5 and FTO) could abnormally overexpressed and exert oncogenic functions or downregulated and play tumour suppressor roles in urologic tumours." (PMID 37284313, 2023). "ALKBH5 and FTO exhibit distinct regulatory roles in hypoxic tumours." (PMID 36859310, 2023). "FTO has been found to play a critical role in tumor cell proliferation, metastasis and apoptosis." (PMID 38094306, 2023). "Histopathological examination also indicated higher FTO levels in tumor tissues." (PMID 36718644, 2023). "HDAC3 initiates tumor activity by regulating the FOXA2-mediated FTO/m6A/MYC axis." (PMID 37932821, 2023). "FTO can inhibit tumor progression in TC by mediating ferroptosis, a form of programmed cell death." (PMID 37915103, 2023).
tumor (continued). "However, in tumor regulation, RNA m6A remains the primary substrate for FTO in cells, as there are many more m6A sites in RNA transcripts than m6Am sites." (PMID 37007161, 2023). "Our results revealed that tumor staging exhibited an independent influence on FTO levels." (PMID 37861518, 2023). "FTO, in turn, can exert tumor suppressive effects by destabilizing MTA1 by removing its m6A." (PMID 37007161, 2023). "In addition to these biological processes, FTO also affect tumorigenesis and progression by regulating other hallmarks of cancer, including cancer stem cell self-renewal, tumor microenvironment, and immunity." (PMID 37915103, 2023). "In addition, we found that FTO expression was significantly negatively correlated with tumor size (p = 0.031) in TCGA database." (PMID 35090515, 2022). "Our integrative bioinformatic analysis suggested that the m6A eraser ALKBH5 might play a tumor-suppressive role in NB compared with another m6A eraser FTO." (PMID 35517412, 2022). "In the current research, we suspected that FTO could act as a tumor suppressor on PCa by regulating the expression of MC4R via a m6A RNA demethylation manner." (PMID 34787056, 2022). "Furthermore, FTO, KIAA1429, WTAP, ZC3H13 were significantly associated with tumor recurrence (P < 0.05)." (PMID 35572524, 2022). "Furthermore, western blotting of FTO in two ESCC samples showed that FTO expression in primary tumor samples was significantly higher than that in the corresponding paracancerous tissues." (PMID 35524932, 2022). "FTO depletion consistently inhibited the tumor growth and decreased the tumor weight." (PMID 35064107, 2022). "In fact, R-2HG exerts its anti-tumor effects via inhibiting FTO enzymatic activity." (PMID 35409166, 2022). "We further validated the accuracy of the Ferr-LPM prediction results with m6a-related lncRNA, such as the FTO protein correlated with lymph node metastasis and tumor grading and METTLE3, which regulated neutrophils and was intimately associated with malignant progression in PTC." (PMID 35915656, 2022). "We observed the xenograft growth for 30 days and found that FTO depletion could significantly suppress the tumor growth in vivo." (PMID 35064107, 2022). "To further assess the clinical significance of FTO-SIK2-autophagy axis promoting ccRCC progression, we examined the expression of FTO and SIK2 in tumor tissues of patients with ccRCC and subsequently categorized the samples into FTO-low and FTO-high groups and determined their relevance in ccRCC." (PMID 36263177, 2022). "Additionally, Niu and colleagues reported that FTO exerted its pro-tumor activity by downregulating the expression of Bcl-2 nineteen kilodalton interacting protein 3 (BNIP3), a pro-apoptotic member of the Bcl-2 family of apoptotic proteins." (PMID 35628623, 2022). "Moreover, studies in vitro and in mouse models confirmed that FTO-specific inhibitors exhibited anti-tumor effects in several cancers." (PMID 35628623, 2022). "Furthermore, our immunohistochemical staining results verified the low expression of FTO in tumor tissues." (PMID 35721711, 2022). "The circRAB11FIP1 might promote tumor autophagy in OC by regulating the m6A methylation of the autophagy-related proteins via FTO." (PMID 36371254, 2022). "In summary, knockdown of FTO can dramatically promote tumor proliferation and metastasis in vivo." (PMID 35397614, 2022). "In addition, FTO is widely involved in regulating the cell cycle, tumour growth, proliferation and migration, stem cell maintenance and other biological processes." (PMID 35518355, 2022). "However, FTO was not indispensable for the growth of HIF2αhigh ccRCC, indicating the different roles of FTO in distinct genetic backgrounds of one tumor." (PMID 35945194, 2022). "Furthermore, overexpression of FTO significantly reduced TPC1 tumor growth and tumor weight in xenograft mouse models." (PMID 35090515, 2022).
tumor (continued). "In addition, the increasing evidences showed that overexpression of FTO in a variety of tumor tissues was highly correlated with the prognosis of tumors." (PMID 35524932, 2022). "FTO knockout can induce G0/G1 phase arrest and inhibit tumor proliferation and growth in vivo." (PMID 35022030, 2022). "Furthermore, reduced FTO in combination with m6A modification of APOE can modulate the IL-6/JAK2/STAT3 signaling pathway to promote tumor glycolysis, thereby aggravating the progression of PTC." (PMID 36506554, 2022). "Collectively, FTO is a critical determinant of tumor progression." (PMID 35568876, 2022). "In bladder cancer, FTO promoted the proliferation of tumor cells in an m6A-dependent manner." (PMID 37529797, 2022). "Notably, the commencement of tumor formation in the FTO-depleted cells was remarkably delayed, and this was further reflected in substantially reduced tumor volume and weight compared with the xenografts with NTC or parental PC cells." (PMID 36497402, 2022). "VHL deficient cells with FTO expression increase PGC-1α expression by reducing m6A methylation level, which can recovery mitochondrial activity, promote oxidative stress and ROS production, thus inhibiting tumor growth." (PMID 35022030, 2022). "However, our findings indicated that circGPR137B acted as a tumor suppressor in HCC by sponging miR-4739/FTO axis." (PMID 35858900, 2022). "Firstly, we found that FTO knockdown could notably enhance cell growth, indicating that FTO may be tumor suppressor in LUAD." (PMID 35945194, 2022). "Moreover, in vivo studies have also shown that several selective FTO inhibitors can significantly inhibit tumor growth and prolong survival in mice." (PMID 35628623, 2022). "More importantly, we validated that the small molecule inhibitor FB23-2 targeting FTO could significantly inhibit tumor growth and prolong the survival time of mice in the PDX model analysis." (PMID 36263177, 2022). "FTO is well known to be involved in tumor progression by regulating m6A levels of target genes." (PMID 37529797, 2022). "Furthermore, FTO depletion in PC cells weakened their tumor-forming capabilities in nude mice; those tumors had increased apoptosis, decreased proliferation markers, and MET conversion." (PMID 36497402, 2022). "However, recent studies have shown that FTO knockdown can increase tumor sensitivity to anti-PD-1 immunotherapy, thereby improving efficacy." (PMID 35707365, 2022). "Thus, FTO have been highlighted as a novel player in tumor development and progression by acting as tumor suppressor or oncogene, depending on the circumstance." (PMID 35397614, 2022). "Briefly, we firstly found FTO was upregulated in cell lines and tumor tissues of ccRCC." (PMID 35961973, 2022). "FTO function in different cancers is context-dependent, whereby FTO may function as a tumor promoter or suppressor by regulating various tissue-specific targets involved in unique pathways pertaining to different cancer types." (PMID 35409166, 2022). "In conclusion, these data supported that FTO exerted the anti-tumor effect and PHF1 overexpression could reverse the tumor progression of FTO-deficient LUAD in vitro and in vivo." (PMID 35945194, 2022). "Moreover, the FTO protein level was significantly increased in the tumor tissues of FTO overexpression group." (PMID 35568876, 2022). "It was speculated that FTO might function as a tumor suppressor gene in PCa, which was confirmed by qRT-PCR and Western blot assays." (PMID 34787056, 2022). "These provided convincing evidence for FTO as a tumor suppressor in PCa." (PMID 35397614, 2022). "In the nude mice model, knockdown of FTO drastically motivated tumor proliferation and metastasis." (PMID 35397614, 2022). "Inhibition of FTO can significantly reduce lactic acid produced by the glycolysis of tumor cells." (PMID 36387147, 2022).